BRCA1 (BRCA1 DNA repair associated)
Diseases named in the same sentence as BRCA1 in open-access papers (continued):
Sharing a sentence is not in itself a finding about the gene and the disease.
ovarian carcinoma (continued). "Additional research is required to investigate and confirm the significance of BRCA1/BRCA2 reversion mutations in ovarian cancer." (PMID 39492906, 2024). "Conversely, in women, with BRCA1/2 gene mutations, the risk for ovarian cancer is strongly reduced by OC use via exerting an advantageous estrogen-like effect by the indirect activation of the AF2 domain." (PMID 38672654, 2024). "Those who have inherited BRCA1 mutations have an increased risk of developing breast and ovarian cancer during their youth." (PMID 38542081, 2024). "For ovarian cancer, the cumulative risk in carriers of BRCA1 PV is low under the age of 45 years but reaches more than 10% by the age of 55 years, whereas it remains low until the age of 65 years for BRCA2 mutation carriers." (PMID 38333895, 2024). "HRR genes mutations were seen in 21.89% patients, with BRCA1/2 mutations significantly enriched in tumors with breast/ovarian cancer family history (P = 0.025) and high Ki-67 levels (P = 0.018)." (PMID 39026672, 2024). "Genetic cancer risk assessment (GCRA) is recommended for women with a personal or family history of breast or ovarian cancer who are at risk of carrying deleterious mutations of the BRCA1/2 genes." (PMID 39240499, 2024). "In this regard, the American Society of Clinical Oncology recommends that all women diagnosed with epithelial ovarian cancer undergo germline genetic testing, especially to detect BRCA1/2 and other genes related to ovarian cancer susceptibility." (PMID 39338246, 2024). "We conducted a prospective study among 989 BRCA1 carriers to assess the association between blood iodine levels and breast and ovarian cancer risk." (PMID 38892720, 2024). "Subsequently, in 2016, rucaparib, a second PARP inhibitor, was authorized for the treatment of patients with advanced-stage ovarian cancers harboring deleterious BRCA1/2 mutations who had received two or more prior lines of chemotherapy." (PMID 38763973, 2024). "Breast cancer type 1 susceptibility protein (BRCA1), a tumor suppressor gene commonly mutated in breast and ovarian cancer, plays a critical role in maintaining genomic integrity." (PMID 38339062, 2024). "Germline genetic testing in women diagnosed with EOC demonstrated that ~ 13.5% carry a pathogenic variant (PV) that increases ovarian cancer risk; ~11% in BRCA1/2 and ~ 2.5% in other moderate penetrant genes such as RAD51C/D, BRIP1, and PALB2." (PMID 38907139, 2024). "Mutations within the BRCT domain can disrupt the normal function of BRCA1 and lead to an increased risk of developing breast and ovarian cancer." (PMID 38543119, 2024). "For example, the incidence of BRCA1 mutations is significantly elevated in breast and ovarian cancers, which coincide with an elevated expression of GSTM5 in these normal tissues when compared to organs like the liver and kidney." (PMID 38247798, 2024). "In the COSMIC database PTEN (11%), PIK3CA (11%) and ARID1A (4%) mutations all occur in BRCA1 mutated ovarian cancer." (PMID 38940864, 2024). "A sequencing study revealed the presence of BRCA1/BRCA2 reversion mutations in cfDNA in 21 % of ovarian cancer patients who were resistant to therapy." (PMID 39492906, 2024). "The cumulative risks of developing ovarian cancer by the age of 70 differ among carriers of BRCA1 and BRCA2 mutations." (PMID 38391958, 2024). "The best example is germline mutations in BRCA1, which predispose female patients to developing ovarian cancer or breast cancer." (PMID 38247798, 2024). "Hereditary BRCA1 or BRCA2 germline mutations have been identified in 5% to 10% of epithelial ovarian cancers, although tumor development in these individuals requires somatic inactivation of the remaining wild-type (WT) allele." (PMID 39028933, 2024). "Individuals with a germline mutation in BRCA1 exhibit a chance of 48.3% for ovarian cancer by 70 years old (95% confidence interval [CI] = 38.8–57.9%) and of 20% (95% CI = 13.3–29.0%) when the mutation is in BRCA2." (PMID 38641594, 2024).
ovarian carcinoma (continued). "In this study, we conducted a comprehensive analysis using publicly available datasets to elucidate the molecular mechanisms driving PARPi resistance in BRCA1-deficient ovarian cancer." (PMID 39408764, 2024). "It was first approved as a maintenance therapy for recurrent high-grade platinum-sensitive ovarian cancer in BRCA1/2-mutated patients." (PMID 37815561, 2024). "HR deficiency associated mutational signatures were first identified in breast and ovarian cancer, which harbor the highest frequency of BRCA1/2 inactivating events." (PMID 38589664, 2024). "SOLO2/ENGOT-Ov21 is a double-blind, randomized, placebo-controlled, multicenter, Phase III clinical trial that compared the efficacy of olaparib tablets as maintenance therapy in platinum-sensitive recurrent ovarian cancer patients with BRCA1/2 mutations." (PMID 39035742, 2024). "There are no available data dealing with the influence of HRT on the risk of recurrence after treatment of ovarian cancer in BRCA1/2-pV carriers." (PMID 39259360, 2024). "Familial cases of breast and ovarian cancer often involve mutations in the tumor suppressors BRCA1 (breast cancer type 1 susceptibility protein) and BRCA2 (breast cancer type 2 susceptibility protein)." (PMID 39767562, 2024). "Genetic testing for BRCA1/2 is recommended for individuals at high risk of hereditary breast and ovarian cancer, yet racial and ethnic disparities persist." (PMID 38730719, 2024). "Among Chinese ovarian cancer patients, the prevalence of deleterious germline BRCA1/2 mutations is about 16.7–28.5% in different studies." (PMID 38509102, 2024). "Currently, Olaparib is a promising targeted drug as first-line maintenance monotherapy for ovarian cancer, which had a BRCA1/2 mutation 1 and maintenance treatment of platinum-sensitive recurrent ovarian cancer." (PMID 38356722, 2024). "A prominent example is the stratification of epithelial ovarian cancer (EOC) patients with homologous recombination deficiency (HRD) characterized by mutations in DNA damage repair genes such as BRCA1/2 for treatment with PARP inhibitors." (PMID 39839766, 2024). "Most of the available information relates to BRCA1-linked disease because BRCA1 germline mutations are approximately four times more common in ovarian cancer patients than BRCA2 mutations." (PMID 39502381, 2024). "The BRCA1-deficient UW and BRCA1-proficient UW + B1 ovarian cancer cell lines were treated for 72 h with increasing concentrations of HU and increasing concentrations of UBC13i." (PMID 38943334, 2024). "Ovarian cancer lifetime risk for BRCA1 and BRCA2 carriers is up to 44% and 17%, respectively, compared to 1.5% in the general population." (PMID 39488595, 2024). "The risk of ovarian cancer in BRCA1 mutation carriers, which ranges from 39 to 46% by the age of 70, and for BRCA2 mutation carriers, ranging from 10 to 27% by the same age, underscores the impact of these genetic alterations on disease incidence." (PMID 38543119, 2024). "We describe a multi-generation CRC-affected family segregating pathogenic variants in both BRCA1, a gene associated with breast and ovarian cancer and RNF43, a gene associated with Serrated Polyposis Syndrome (SPS)." (PMID 38063999, 2024). "A germline mutation in the BRCA1 gene predisposes individuals to the development of ovarian cancer, with the mechanism of loss of heterozygosity (LOH) playing a key role in this process." (PMID 39300540, 2024). "Among 34 individuals with PMMTs, pathogenic variants in the BRCA1 gene occurred in two cases (6%); the other tumors were colorectal and ovarian cancer in one case, and lung cancer in another." (PMID 39684352, 2024). "The aim of this study was to determine the expression of BRCA1 protein in epithelial ovarian cancer (EOC) and the associated clinicopathological characteristics." (PMID 39502381, 2024).
ovarian carcinoma (continued). "BRCA1 is frequently mutated in breast and ovarian cancers and plays important roles in multiple processes such as transcription, cell cycle progression, and DNA damage repair." (PMID 39125994, 2024). "Olaparib has been approved for patients with breast, ovarian, pancreatic, or prostate cancer who had HRD or BRCA1/2 mutations with PVs, whereas niraparib has been approved for patients with ovarian cancer who had HRD or BRCA1/2 mutations with PVs." (PMID 39590127, 2024). "In BRCA1/2-deficient models in breast and ovarian cancer, PARPi increased cytosolic DNA and activated cGAS-STING (cyclic GMP-AMP synthase-stimulator of interferon genes) signalling, and upregulated pro-inflammatory chemokines such as CCL5 and CXCL10." (PMID 39201718, 2024). "BRCA1, HFE, and MLH1 are key genes associated with significant health conditions: BRCA1 with breast and ovarian cancers, HFE with hereditary hemochromatosis, and MLH1 with Lynch syndrome, a form of hereditary colorectal cancer." (PMID 38872284, 2024). "Although most studies indicate that BRCA2 mutations are associated with prolonged survival in invasive epithelial ovarian cancer, we presented a case of a patient with BRCA1 mutation and extended survival benefit." (PMID 39272683, 2024). "Given the well-established association of BRCA1 mutations with breast and ovarian cancers in females, it is imperative to elucidate the sex-specific epigenetic mechanisms that regulate BRCA1 in girls." (PMID 39358554, 2024). "Initially, PARP inhibitors were developed for treating BRCA1/2-deficient breast and ovarian cancers due to the synthetic lethality relationship between BRCA1/2 and PARP." (PMID 37253984, 2024). "Most hereditary ovarian cancer cases are attributed to germline mutations in the BRCA1 or BRCA2 genes." (PMID 39338246, 2024). "Carriers of BRCA1 PGVs show: (i) an absolute risk of BC higher than 60%; (ii) an absolute risk of male BC ranging from 0.2 to 1.2%; and (iii) an absolute risk of epithelial ovarian cancer ranging from 39 to 58%." (PMID 38672070, 2024). "As reported in many studies, BRCA1 mutations are responsible for a large increase in the lifetime risk of breast and ovarian cancers, and plays a role in targeting prophylactic interventions and treatment." (PMID 39595122, 2024). "BRCA1/2 were the most common variants identified from the comprehensive panel, resulting in a positive rate of 13% for genes historically associated with ovarian cancer only." (PMID 39061202, 2024). "Female BRCA1/2 pathogenic variant (PV) carriers face substantial risks for breast and ovarian cancer." (PMID 39446752, 2024). "BRCA1/2 mutations are central in homologous recombination repair deficiency (HRD) in ovarian cancer, but several other genetic mutations also contribute to varying cancer risks." (PMID 39457020, 2024). "A reduction in ovarian cancer risk following the use of oral contraceptives has also been observed for carriers of pV in BRCA1 or BRCA2 genes in several studies." (PMID 39259360, 2024). "In this study, we have defined breast and ovarian cancer risk estimates for BRCA1 and BRCA2 PV carriers in Malaysia and Singapore." (PMID 38333895, 2024). "A BRCA1 mutation increases the lifetime risk of breast cancer with up to 70% and of ovarian cancer with up to 40%." (PMID 38732616, 2024). "The lifetime risks of developing breast and ovarian cancer in female BRCA1 mutation carriers are reported to be 72% and 44%, respectively, by the age of 80." (PMID 39590130, 2024). "A retrospective cohort study from 2015 showed an increase of ovarian cancer risk following HRT both for pV-carriers in the BRCA1 gene (OR 1.66; 95% CI 0.89–3.08; p < 0.001) and in the BRCA2 gene (OR 3.04; 95% CI 1.19–7.8; p < 0.001)." (PMID 39259360, 2024). "This drug is mainly indicated for ovarian cancer, fallopian tube cancer, peritoneal cancer, pancreatic cancer, and prostate cancer with hereditary or somatic BRCA1 or BRCA2 mutation." (PMID 37815561, 2024).
ovarian carcinoma (continued). "Currently, in southwestern Finland, the amount of pathogenic BRCA1/2 variants is approximately 10% in all high-risk breast and ovarian cancer families." (PMID 39272813, 2024). "The recommended ovarian cancer control guidelines include discussion of risk-reducing salpingo-oophorectomy (RRSO) at ages 35–40 for BRCA1 carriers and 40–45 years for BRCA2 carriers." (PMID 38333895, 2024). "We present compelling evidence implicating LY6E (lymphocyte antigen 6 complex, locus E; aliases RIGE; SCA2; RIG-E; SCA-2; TSA-1), a member of the Ly-6/uPAR protein family and is a critical mediator of PARPi resistance in BRCA1-deficient ovarian cancer." (PMID 39408764, 2024). "We also used BRCA1-deficient ovarian cancer cell line UWB1 75,76 and showed that acquired Olaparib resistance of UWB1 cells upon 53BP1 depletion can be reverted by inhibiting PIF1." (PMID 39314326, 2024). "BRCA1 knockdown was found to effectively increase NAMPT levels in ovarian cancer cells and primary non-BRCA1-mutated cells, suggesting a critical role for NAMPT in BRCA1-related NAD+ synthesis in ovarian cancer." (PMID 39272943, 2024). "Denosumab, an inhibitor of RANKL (an NF-κB ligand) and NF-κB signaling, was evaluated in ovarian cancer patients with BRCA1 mutations." (PMID 38539161, 2024). "Pathogenic variants in the BRCA1 gene greatly increase the risk of developing breast and ovarian cancer at a young age." (PMID 38786046, 2024). "Elevated blood molybdenum levels are associated with an increased risk of ovarian cancer on BRCA1 mutation carriers." (PMID 39300540, 2024). "Consistently, our findings on ovarian cancer reveal higher prevalences of BRCA1 and BRCA2 mutations in subtypes 1 and 3, which are associated with better survival and responses to treatments compared to subtype 2." (PMID 39199616, 2024). "Epithelial ovarian cancers harbouring a germline BRCA1/2 mutation are highly sensitive to platinum-containing chemotherapy." (PMID 39550490, 2024). "Maintenance therapy using PARP inhibitors is increasingly being recognized as a paradigm shift in the treatment of patients with advanced ovarian cancer, particularly those harbouring BRCA1/2 mutations or HRD." (PMID 39360040, 2024). "In a parallel context, ovarian cancer patients demonstrate a similar proportion (15.4%) of BRCA1 mutations." (PMID 39217242, 2024). "The cumulative risk (95% CI) of ovarian cancer to age 80 was 31% (27–36%) for BRCA1 carriers and 12% (10–15%) for BRCA2 carriers." (PMID 38333895, 2024). "Reversion of BRCA1/2 mutation can lead to clinical PARPi resistance in BRCA-germline mutated ovarian cancer." (PMID 39135999, 2024). "Approximately 20 years ago in Finland, pathogenic BRCA1/2 variants were observed in 25% of high-risk breast and ovarian cancer families." (PMID 39272813, 2024). "The association between BRCT domain mutations and ovarian cancer is particularly relevant to BRCA1’s essential role in maintaining genomic stability and repairing DNA damage." (PMID 38543119, 2024). "Mutations in BRCA1/2 substantially increase the risk of ovarian cancer, with a risk range of 39–63% in BRCA1 mutation carriers and 16.5–27% in BRCA2 mutation carriers." (PMID 38541242, 2024). "According to a domestic study, the breast and ovarian cancer risks of BRCA1 mutation carriers up to the age of 70 were 72.1% and 24.6%, respectively, and 66.3% and 11.1%, respectively, in BRCA2 mutation carriers." (PMID 39590130, 2024). "Fallopian tube organoids derived from iPSCs of ovarian cancer patients carrying BRCA1 mutations showed cell abnormalities consistent with tumor development." (PMID 39333482, 2024). "Women carrying these mutations face a significantly elevated risk of developing ovarian cancer, with percentages of 50% or more for BRCA1 and 20% for BRCA2." (PMID 39338246, 2024).
ovarian carcinoma (continued). "It has been recently reported that an orally bioavailable dual inhibitor of ATM and DNA-PKcs kinases synergized with PARP inhibitors in BRCA1/2-deficient models, including UWB1.289, a BRCA1-mutant human ovarian cancer cell line." (PMID 39594684, 2024). "Onvansertib, a highly selective PLK1 inhibitor, and olaparib were tested in vitro and in vivo in BRCA1 mutated and wild-type (wt) ovarian cancer models, including patient-derived xenografts (PDXs) resistant to olaparib." (PMID 39039067, 2024). "The rates of breast/ovarian cancer surveillance, chemoprevention, and risk-reducing surgery were low among unaffected Korean BRCA1/2 mutation carriers." (PMID 39590130, 2024). "The circulating cell-free DNA (cfDNA) sequencing analysis can help identify BRCA1/2 reversal mutations in breast and ovarian cancer patients." (PMID 37588193, 2024). "A previous study identified gBRCA1/2 mutation as a risk factor for ovarian cancer brain metastasis, particularly the BRCA1 mutation, with 68.2 % (15 of 22 patients) showing loss of BRCA1 expression in the tumor." (PMID 39035033, 2024). "BRCA-positive patients were defined as those with likely pathogenic and/or pathogenic mutations in BRCA1/2, and 103 (8.8%) out of 1171 ovarian cancer patients were BRCA-positive." (PMID 38817903, 2024). "In conclusion, to date, no valid assessment regarding potential differences in the effects of different HRT or HC regimens on breast or ovarian cancer risk of BRCA1/2 pathogenic variant carriers and the general population can be given." (PMID 38892081, 2024). "Germline BRCA1 or BRCA2 mutations yield ovarian cancer, most often HGSOC, with a lifetime unmitigated risk of 30% to 70%." (PMID 39225558, 2024). "Within the trial, 30% of patients had known deleterious germline BRCA1/2 mutations and 90% of study population had primary or acquired platinum-resistant and refractory ovarian cancer." (PMID 38245661, 2024). "Germline BRCA1/2 mutations are identified in up to 15% of serous ovarian cancer, while an additional 5–7% of ovarian cancers harbor somatic BRCA1/2 mutations." (PMID 38893083, 2024). "To further explore the potential function of DNA-PK-i in cancer treatment, we treated BRCA1-deficient UWB1 ovarian cancer cells with combination of low dose DNA-PK-i (M3814) with Pol I-i (BMH-21)." (PMID 38682589, 2024). "While initially focusing on BRCA1/2-variant families, Hebon gradually expanded to include pathogenic variants in other genes associated with breast and/or ovarian cancer over time." (PMID 39384226, 2024). "The second case exemplifies the complexities and potential triumphs of managing a case of advanced ovarian cancer with BRCA1 mutation, with the transformative impact of PARP inhibitors in oncology." (PMID 39272683, 2024). "Increasing genetic referral and expanded testing resulted in higher estimated rates of risk-reducing surgery and lower incidence of breast and ovarian cancer in relatives of probands with a P/LP variant in BRCA1, BRCA2 or PALB2." (PMID 39766065, 2024). "High blood lead levels are associated with increased risk of ovarian cancer in BRCA1 carriers, suggesting priority for preventive salpingo-oophorectomy." (PMID 38732616, 2024). "Extensive research has focused on BRCA-1 gene mutations across various malignancies, such as breast cancer, lung cancer, and ovarian cancer." (PMID 39281319, 2024). "This ability of PARPi to enhance radiosensitivity has been extensively studied in tumors with BRCA1/2 deficiencies, particularly in hereditary breast and ovarian cancers." (PMID 37629155, 2023). "Female BRCA1/2 pathogenic variant carriers have an increased lifetime risk for breast and ovarian cancer." (PMID 37185387, 2023). "Epidemiological studies show that women with deleterious germline mutations in BRCA1 or BRCA2 gene have a higher lifetime risk of ovarian cancer." (PMID 37386498, 2023).